RCC2 (regulator of chromosome condensation 2)
Diseases named in the same sentence as RCC2 in open-access papers (continued):
Sharing a sentence is not in itself a finding about the gene and the disease.
tumor (continued). "Cytoplasmic and nuclear expression of RCC2 were correlated among tumours (Pearson’s r=0.77); however, cytoplasmic RCC2 staining was more strongly associated with patient outcome." (PMID 33219056, 2020). "Consistent with in vitro results, silencing of RCC2 markedly reduced tumor size and weight as compared to the scramble group." (PMID 31839818, 2019). "In summary, these results suggest that silencing of RCC2 significantly attenuates xenograft tumor progression and metastatic potential in vivo." (PMID 31839818, 2019). "In this study, we found that RCC2 plays a role in tumor cell death by blocking the Rac1- initiated apoptosis." (PMID 29321004, 2018). "Further studies showed that RCC2 over-expression in tumor cells led to attenuation of spontaneous- or STS-induced apoptosis and the apoptosis resistance was associated with decreased Rac1 activation." (PMID 29321004, 2018). "RCC2 expression on tumor tissue microarrays was studied using a 5-tier scoring system (−, −/+, +, ++, +++) depending on signal intensity." (PMID 29321004, 2018). "Tumor cells with forced RCC2 expression indeed had significant difference in drug sensitivity compared to parental cells using a panel of common chemotherapeutic drugs." (PMID 29321004, 2018). "Forced RCC2 expression in tumor cells blocked spontaneous- or Staurosporine (STS)-induced apoptosis." (PMID 29321004, 2018). "RCC2 was mainly localized in the nuclei of tumor cells, although some had significant cytoplasmic RCC2 in addition to nuclear localization." (PMID 29321004, 2018). "RCC2 expression was significantly higher in metastatic ovarian cancers (P < 0.05), higher grade tumors (P < 0.05) and bigger tumor (P < 0.05)." (PMID 29321004, 2018). "The data showed that overexpression of miR-1247 mimics decreased RCC2 expression in the tumor tissues compared to control tissues." (PMID 28460450, 2017). "These evidences support SBDA inhibits tumor cell proliferation via targeting RCC2 lactylation." (PMID 40145796, 2025). "RCC2 and ALDH18A1 high expression have been confirmed associated with tumor progression." (PMID 39908861, 2025). "It is indicated that RCC1 and RCC2 might mediate tumor progression and RCC2 may play an important role in regulation of immunotherapeutic effects on LUAD." (PMID 38434981, 2024). "Mechanistically, our results indicate that the tumor suppressive phenotype elicited upon IER5L targeting is associated to changes in the transcriptional program of proliferation and monomeric G protein regulators such as RCC2 and ARHGEF1." (PMID 39025841, 2024). "In addition, Xenograft lung metastasis tumor model showed that knockdown of circATIC suppressed BLca metastasis in vivo, whereas forced expression of RCC2 relieved this effect." (PMID 38993556, 2024). "Therefore, RCC1 and RCC2, serving important roles in tumor progression, have the potential to be prognostic biomarkers for LUAD." (PMID 38434981, 2024). "Our result indicated that RCC2 might participate in tumor immune reaction through media immune cell infiltration." (PMID 38434981, 2024). "In other words, RCC2 promotes tumor growth by promoting Gli1." (PMID 38008751, 2023). "Meanwhile, IPS scores also play a critical role in predicting the response of cancer patients to ICI, and we can observe that high expression of RCC2 in some cancers leads to a decrease in immune scores, which may lead to rapid tumor progression." (PMID 36441563, 2022).
tumor (continued). "In addition, the RCC2 had a potential role in regulating the tumor immune microenvironment and the formation of cancer-associated fibroblasts (CAFs)." (PMID 36441563, 2022). "RCC2 is thought to be a regulator of cell migration and tumor metastasis." (PMID 36441563, 2022). "Therefore, RCC2 inhibits tumor cell metastasis by inhibiting activation of small GTPases, Rac1, and Arf6, and by promoting α5β1-FN-signaling network and cellular recognition to FN concentrations." (PMID 33521058, 2020). "Therefore, RCC2 plays a vital role in tumor proliferation, tumorigenicity, and promotes radioresistance by activating transcription of DNA methyltransferase 1 (DNMT1) through a p-STAT3 dependent pathway." (PMID 33521058, 2020). "Therefore, overexpression of RCC2 in tumor cells prevents cellular apoptosis and promotes chemotherapeutic resistance by blocking Rac1 signaling." (PMID 33521058, 2020). "This is the first study demonstrating the importance of RCC2 for tumor growth in an animal model." (PMID 32565805, 2020). "Thus, investigating the tumorigenic mechanism of RCC2 is helpful for understanding tumor growth mechanisms." (PMID 32565805, 2020). "Low RCC2 expression was more frequently found in microsatellite stable (MSS) tumours, although this association was not significant by the new RCC2 scoring method with monoclonal antibody and digital analysis (p=0.06)." (PMID 33219056, 2020). "However, low protein expression level of RCC2 is associated with poor prognosis of MSS, which is attributed to its functional inhibition of tumor cell metastasis by regulating integrin α5β1-fibronectin (FN) signaling pathway." (PMID 33521058, 2020). "RCC2 functions as an oncogene in numerous kinds of cancers by promoting progression of tumor cells, facilitates metastatic behaviors and induces therapeutic resistance in tumor cells." (PMID 33521058, 2020). "Recently, RCC2 has been identified as a regulator of cellular migration and tumor metastasis." (PMID 31839818, 2019). "RCC2 expression in tumor can be a useful marker for predicting chemotherapeutic response." (PMID 29321004, 2018). "We then co-transfected tumor cells with both RCC2-YFP and a constitutively activated Rac1-Q61L." (PMID 29321004, 2018). "Similarly, ENST00000439577 and RCC2 expression were higher in tumor than in adjacent non-tumor tissues, and ENST00000439577 and RCC2 expression were positively correlated (r = 0.288, P = 0.011)." (PMID 27849024, 2016). "Moreover, we analyzed the prognostic value of RCC2 in different tumor types." (PMID 36441563, 2022). "Therefore, RCC2 knockdown inhibits tumor progression and metastatic potential in vivo and in vitro." (PMID 33521058, 2020). "Therefore, RCC2 regulating tumor cell metastasis by activating a series of signaling pathways." (PMID 33521058, 2020). "RCC2 silencing partially reversed NaLa‐induced proliferation in MTT and colony formation assays, which was confirmed by xenograft tumor size and Ki‐67 staining." (PMID 40145796, 2025). "Meanwhile, RCC2 showed a significant correlation with TMB, MSI, chemokines and their receptors in different tumor types." (PMID 36441563, 2022). "Overall, these results indicate that a SIAH1–YBX-1-E2F5/YY1/RCC2 axis exists and that this axis plays an essential role in regulating the DDP sensitivity and tumor suppressor function of SIAH1." (PMID 35273154, 2022). "The expression of RCC2 in ER-positive breast induces the expression of IGF-1 and leads to the malignant behavior of tumor cells, including proliferation, invasion, etc.." (PMID 33750478, 2021). "A recent study shows that RCC2 expression promotes estrogen receptor-positive (ER+) breast tumorigenesis by increasing expression of IGF1 and TWIST1, tumor-enhancing genes, and IL-6." (PMID 33521058, 2020).
tumor (continued). "The interaction between RCC2 and adjuvant chemotherapy for prediction of patient outcome was significant in stage III, and strongest among patients with microsatellite stable tumours (pinteraction=0.028)." (PMID 33219056, 2020). "MCF-7 cells were also transfected with lentivirus-containing anti-RCC2 short hairpin RNA and were injected into BALB/c nude mice to generate tumor-bearing mice." (PMID 32565805, 2020). "Because chemotherapeutic drugs can kill tumor cells by activating Rac1/JNK pathway, we suspect that tumors with RCC2 overexpression would be more resistant to these drugs." (PMID 29321004, 2018). "In mouse xenografts, RCC2 KO increased lung metastasis without significantly affecting primary tumor growth, while CD24 KO reduced both tumor growth and metastasis." (PMID 41090358, 2025). "Mechanistically, RCC2 induced cell growth, EMT, CSCs markers through Gli1; inhibiting Gli1 expression using siGli1 or GLI inhibitor suppressed cell progression in vitro and tumor growth in vivo." (PMID 38008751, 2023). "Furthermore, in the tumor-bearing mouse model, we detected low levels of IGF1 and TWIST1 expression in tumors originating from MCF-7 cells transfected with anti-RCC2 shRNA." (PMID 32565805, 2020). "PCR array demonstrated that inhibiting RCC2 expression significantly decreased the expression of IGF1 and TWIST1, two well-known tumor-enhancing genes, in MCF-7 cells; conversely, overexpressing RCC2 increased the expression levels of these two genes in the transfected cells." (PMID 32565805, 2020). "We report on the establishment of a robust protocol for RCC2 expression analysis and prognostic tumour biomarker evaluation in patients who did and did not receive adjuvant chemotherapy." (PMID 33219056, 2020). "Because of the importance of Rac1 in apoptosis, and because RCC2 expression effectively blocked Rac1 activation, it is not surprising that tumor cells with forced RCC2 expression reacted differently to drug-induced apoptosis." (PMID 29321004, 2018). "Obviously, RCC1 and RCC2 expressed higher protein level in tumor tissues than in normal tissues." (PMID 38434981, 2024). "In fact, RCC2 was found to be an independent prognostic biomarker in multivariable analysis of chemotherapy-untreated stage I–III patients, after adjusting for TNM stage, patient age, sex, tumour location, MSI status, CDX2 expression, BRAFV600E- and KRAS mutation status." (PMID 33219056, 2020). "Furthermore, to delineate whether RCC2 could promote tumor metastasis in vivo, MDA-MB-231-shRCC2 or negative control cells were intravenously injected into nude mice (n=6) via tail vein to establish a liver/lung metastatic model." (PMID 31839818, 2019). "Exploratory analyses suggested that the benefit from chemotherapy in the RCC2-low subgroup was independent of CDX2 expression, but the number of tumours with low CDX2 expression was too small to draw a firm conclusion." (PMID 33219056, 2020).
cancer (20 papers, 2013 to 2025). A tumor composed of atypical neoplastic, often pleomorphic cells that invade other tissues. "It was discovered that prognostic risk model-related three genes, including PASK, PSENEN, and RCC2, were upregulated in cancer tissue compared to normal Breast tissue, as shown in." (PMID 40725242, 2025). "We then investigated the association between RCC2 expression and molecular subtypes throughout pan-cancer using TISIDB’s “subtype” module." (PMID 36441563, 2022). "In our study, we identified the mutations as the main type of genetic alterations in RCC2 in pan-cancers." (PMID 36441563, 2022). "We observed that RCC2 expression was negatively associated with the IPS score among thirteen different cancers, while it was positively associated with the IPS score in OV." (PMID 36441563, 2022). "According to the ESTIMATE analysis, the correlation of RCC2 expression and immune-associated cell infiltration also occurred in pan-cancer." (PMID 36441563, 2022). "We used STRING and GEPIA2 to create a protein interaction network for RCC2 and obtain RCC2-associated genes and performed enrichment analysis to investigate the potential molecular mechanisms of RCC2 in cancer occurrence and development." (PMID 36441563, 2022). "Among the immunostimulatory factors, IL6R, TNFRSF18, TNFRSF25, and ULBP1 were significantly associated with RCC2 expression in the majority of cancer types." (PMID 36441563, 2022). "Extensive studies provide in-depth understanding of the functions of RCC2 in development of various cancers, and its association with therapeutic resistance." (PMID 33521058, 2020). "In recent years, RCC2 has been considered to be related to increased risk of many cancers, but there have been few reports on the effect of RCC2 on breast tumorigenesis." (PMID 32565805, 2020). "In conclusion, RCC2 is closely associated with tumorigenesis and cancer-immune infiltration, and could be a promising prognostic and therapeutic biomarker in diverse cancers." (PMID 36441563, 2022). "Besides, the expression level of RCC2 in pan-cancer was significantly associated with the cancer immune microenvironment." (PMID 36441563, 2022). "However, the association between low RCC2 expression and poor prognosis in chemotherapy-untreated cancers was strong also in stage II, suggesting a potential to improve the outcome of patients in the low-RCC2 subgroup also in this stage." (PMID 33219056, 2020). "Previous studies have explored the mechanism of RCC1 and RCC2 in other kinds of cancers, which is mainly ascribed to its regulation of numerous signaling pathways." (PMID 38434981, 2024). "RCC2 has been involved in the etiology of various cancers and has been shown to be a biomarker for colorectal cancer." (PMID 38182794, 2024). "As expected, the mRNA level of RCC2 was dramatically increased in malignant tumor tissue compared with para-carcinoma tissue (P <0.01)." (PMID 38434981, 2024). "Recently, many reports showed that RCC2 is involved in many human cancers, functioning as an oncogene to promote cancer progression, tumorigenesis, and drug resistance." (PMID 38008751, 2023). "Currently, RCC2 has only been reported in some specific tumors, and there is still no clear evidence of its regulatory role and molecular mechanism in pan-cancer." (PMID 36441563, 2022). "Differences in mRNA expression levels of the RCC2 in various cancer types indicated its diverse roles in cancer development." (PMID 36441563, 2022). "The present study revealed that RCC2 was overexpressed in the majority of cancer tissues and affects clinical prognosis." (PMID 36441563, 2022). "Although there have been reported in several individual tumors, an integrative analysis of RCC2 and its clinical significance across diverse cancer types is poorly elucidated." (PMID 36441563, 2022).
cancer (continued). "Recently, several studies have shown that the RCC2 is participated in the pathophysiological processes of cancers in different ways." (PMID 36441563, 2022). "In the present study, we analyzed the results by using data from the TIMER2.0 database showing that RCC2 was overexpressed in most types of cancer relative to normal tissue, while it was only found to be downregulated in KICH." (PMID 36441563, 2022). "We further revealed that the expression of RCC2 was negatively related to immunomodulators in most cancers." (PMID 36441563, 2022). "The different outcomes of RCC2 expression in diverse cancers prompted further exploration of its specific role in individual cancer." (PMID 36441563, 2022). "In this study, we performed integrative bioinformatics analyses to profile the expression landscape and assess the prognostic value of RCC2 in pan-cancers." (PMID 36441563, 2022). "In summary, RCC2 plays an important role in cell cycle, cancer development, and therapeutic resistance of anticancer drugs." (PMID 33521058, 2020). "Taken together, RCC2 promotes therapeutic resistance in most cases via interacting with various signaling pathways, which resulted in poor effects in cancer treatment." (PMID 33521058, 2020). "TCGA RNA-seq expression data further confirmed the higher RCC2 expression in cancer as compared to normal tissues." (PMID 31839818, 2019). "EMT is a prerequisite physiological process for metastasis in most cancers and several studies have suggested the association of RCC2 and EMT in cancer malignancy." (PMID 31839818, 2019). "In the three cancer cell lines tested, forced RCC2 expression led to drug resistance to most chemotherapeutic reagents, although increased sensitivity was also observed in some settings." (PMID 29321004, 2018). "Three cancer cell lines with up- or down-regulation of RCC2 were used to evaluate cell proliferation, apoptosis, Rac1 signaling and sensitivity to a group of nine chemotherapeutic drugs." (PMID 29321004, 2018). "Additionally, studies on other cancers confirmed a poor prognostic significance of RCC2 expression and demonstrated its role in cell division, cell cycle progression, cell migration, metastasis, and cancer promotion." (PMID 39118792, 2024). "We further validated the expression of RCC2 from proteomics data of 16 different cancer types." (PMID 36441563, 2022). "Firstly, we applied the TIMER2.0 website to evaluate the RCC2 expression in pan-cancer." (PMID 36441563, 2022). "We found that RCC2 was significantly overexpressed in the majority of tumors and may contribute to the development of cancers." (PMID 36441563, 2022). "We then examined the genetic alterations of RCC2 in pan-cancers by using the cBioPortal database." (PMID 36441563, 2022). "There are few studies on RCC2 gene alterations in pan-cancers." (PMID 36441563, 2022). "Meanwhile, TISIDB data showed considerable differences in RCC2 expression in distinct cancer immune subtypes, implying that RCC2 may serve as a valid biomarker for differentiating immune subtypes." (PMID 36441563, 2022). "Besides, we also found that RCC2 protein was abnormally expressed in many cancer types from the HPA database." (PMID 36441563, 2022). "Our comprehensive analysis highlighted the possibility of RCC2 as a promising biomarker for diagnosis and therapy and may contribute to the precision and individualized cancer therapeutic strategies." (PMID 36441563, 2022). "Expression level of RCC2 is significantly high in most common cancer types." (PMID 33521058, 2020). "Therefore, RCC2 is a potential biomarker for development of new and specific anti-cancer therapeutic strategies." (PMID 33521058, 2020). "Therefore, this review explores the functions of RCC2 in cell cycle and roles of RCC2 in cancer progression." (PMID 33521058, 2020). "Notably, RCC2 is highly expressed in several cancer types, including breast, ovarian, lymphoma, cervical, breast, gastric, colorectal, lung, and liver cancer." (PMID 33521058, 2020).